ARG1 (arginase 1)
Diseases named in the same sentence as ARG1 in open-access papers (continued):
Sharing a sentence is not in itself a finding about the gene and the disease.
tumor (continued). "In tumor-associated myeloid cells, upregulation of ARG1 has been shown to reduce inflammation by suppressing T-cell proliferation through arginine deprivation." (PMID 34480465, 2022). "We developed a nomogram based on ARG1 expression levels, combined with different tumor parameters, to predict the risk of early TACE refractoriness in unresectable HCC patients treated with TACE." (PMID 36212404, 2022). "Increased L-arginine metabolism by arginase-1 released from TANs (predominantly N2 neutrophils) in the tumor microenvironment has been associated with T cell immunosuppression in mice and humans." (PMID 34637051, 2022). "Other myeloid cells were also shown to produce ARG1, including tumour-associated macrophages (TAMs) and neutrophils, however, there are considerable differences between mice and men." (PMID 36010962, 2022). "It is well known that Arginase 1 increases the immunosuppressive function of tumor-associated macrophages (TAM)." (PMID 36428642, 2022). "To assess which types of macrophages are impacted by the loss of Gli2/Gli3, we evaluated the expression of arginase 1 (ARG1), a marker of immunosuppressive tumor-associated macrophages (TAMs)." (PMID 35867772, 2022). "CD206 is a marker of glutamine metabolism, CD163 is a marker of iron metabolism, and ARG1 is associated with tumor-derived lactic acid." (PMID 35350571, 2022). "In this study, we developed a nomogram based on ARG1 expression level, combined with different tumor parameters, to predict the risk of early TACE refractoriness in patients with unresectable HCC." (PMID 36212404, 2022). "For example, it is widely accepted that arginase 1-expressing and polyamine-producing tumor-associated M2 macrophages (TAM2) support pro-oncogenic functions and are pathogenic in cancer." (PMID 35053375, 2022). "ARG1 expression is linked with increased tumor growth and immune suppression and serves as a prognostic biomarker in a wide range of human cancers." (PMID 36091114, 2022). "Tumor cells can promote the differentiation of ARG1-expressing cells such as tumor-associated macrophages (TAMs) and myeloid-derived suppressor cells (MDSCs) to evade immune surveillance." (PMID 36330525, 2022). "Lactate also increases VEGF and Arginase 1 expression in tumor-associated macrophages, polarizing these cells toward the immunosuppressive, tumor-promoting M2 phenotype." (PMID 36531060, 2022). "Knocking-out ARG1 in myeloid cells is associated with slower tumor progression and improved mice survival." (PMID 36385153, 2022). "Lactic acid promotes the expressions of VEGF and Arg1 which leads to the differentiation of tumor-associated macrophages towards M2 subtype." (PMID 36003368, 2022). "Cells in Mac_0 were characterized by expression of complement-related genes (C1qa, C1qb, C1qc) and cytokines (Spp1, Ccl12), while cells in Mac_1 expressed higher levels of several tumor-associated macrophage-related genes such as Arg1, Cebpb, and Ier3." (PMID 34030676, 2021). "In another study, TET2 was reported promoting tumor progression in melanoma via ARG1, an immunosuppressive gene in tumor-associated macrophages." (PMID 34957093, 2021). "MDSCs expressed lower levels of anti-inflammatory Arg1, Il-10, Ccl17, and Ccl22, but produced higher levels of angiogenic factors compared to tumor-associated macrophages." (PMID 33441138, 2021). "Inhibiting arginase-1 in vivo in an NSCLC mouse model caused tumor regression and an improvement of T-cell functions." (PMID 34203451, 2021). "An acidic tumor was associated with a strong increase in the expression of the Arg1 and CD206 genes related to the tumor-promoting phenotype of TAMs." (PMID 34885023, 2021). "It has been shown that PGE2 and TGF-β, both present in TDEs, are also critically involved in the abrogated function of tumor-associated DCs via the upregulation of ARG1 activity, IDO, and co-inhibitory molecule B7-H1 and B7-DC, as well as the IL-10 production." (PMID 34078376, 2021).
tumor (continued). "In the context of cancer, tumour-derived succinate induced migration and IL-6 production in tumour-associated macrophages, but also increased Arg1 expression, a marker of both “M2”-type and tumour-associated macrophages." (PMID 33995417, 2021). "MDSCs mainly exert their suppressive effects by producing arginase-1 (Arg-1) which causes the removal of L-arginine, an essential amino acid for T cell differentiation, from the tumor microenvironment (TME)." (PMID 33562495, 2021). "Our results showed that the expression of ARG1 was markedly upregulated in Mettl3-deficient myeloid cells, enhancing tumour growth and metastasis." (PMID 33654093, 2021). "Arg1 is expressed by tumor cells, myeloid derived suppressor cells and tumor associated macrophages." (PMID 34944584, 2021). "For example, ARG1 and IL-1β were found to be enriched in both tumor-associated microglia and macrophages." (PMID 33766119, 2021). "Arginase enzymes facilitate localized immune suppression mediated by cancer-associated fibroblasts (ARG2), MDSCs, DCs, tumor-associated macrophages (TAMs) and tumor-infiltrating macrophages (ARG1)." (PMID 33747948, 2021). "Tumor-associated neutrophils can induce ARG1-dependent immunosuppression through concomitant exocytosis of gelatinase and azurophil granules." (PMID 34948368, 2021). "TAMs exhibit atendency of upregulation of transcription factor HIF1α, which in turn enhances the expression of vascular endothelial growth factor (VEGF) and arginase-1, underlining the tumor-favoring function of TAMs." (PMID 34868994, 2021). "Lactic acid induces expression of VEGF, Arg1 and other M2 genes in TAMs via HIF-1α stabilization, and this is critical for tumor growth, as Arg1-deficient macrophages impair tumor progression in vivo in a mouse model." (PMID 34079545, 2021). "High expression of ARG1-containing exosomes contributes to tumor growth and tumor escape from the host immune system, and increased ARG1 activity in plasma is associated with worse prognosis in OvCa patients." (PMID 34248988, 2021). "In a cancerous tumor, cytokines, such as IL10, secreted by the cancer cells, and the transcription factor STAT-3, cause induction of the competing enzyme arginase-1 (Arg1) in the tumor-associated microglia and macrophages (TAM)." (PMID 34575998, 2021). "WNT3A derived from GBM induces upregulation of stress-inducible protein 1 (STI1/HOP), interleukin 10 (IL-10), and arginase-1 (ARG-1) in tumor-associated microglia." (PMID 33312955, 2020). "RON activation upregulates Fos by activating MAPK, which binds to the Arg1 promoter AP-1 to induce the expression of Arg1, while Arg1 expression in tumor-associated macrophages is significantly reduced in RON knockout mice." (PMID 33117355, 2020). "In the tumor microenvironment, enhanced expression of Arginase-1 by myeloid cells causes the local depletion of the semi-essential amino acid L-arginine." (PMID 32647818, 2020). "Lactate also mediates M2-like polarization of tumor associated macrophages, which is believed to be tumor supportive, and increases the expression of vascular endothelial growth factor and arginase 1 eventually leading to immune escape." (PMID 32916853, 2020). "C/EBPβ deficiency significantly reduces iNOS and ARG1 in tumor-infiltrating MDSCs, and the suppressive activity of MDSCs is impaired." (PMID 32325683, 2020). "Upregulated arginase 1, leading to the depletion of extracellular arginine, is a hallmark of tumor immunosuppression and an immunomodulatory target in anti-cancer therapy." (PMID 32932854, 2020). "In total, TAMs have a higher expression of VEGF and Arg1 as compared to the other cellular components of the tumor microenvironment, which underlines the tumor-supporting function of TAMs." (PMID 31454887, 2019). "For the tumor-associated macrophage populations, this analysis revealed high expression of the alternative activation markers Arg1, Fizz1, and Mrc1, which coincided with reduced mRNA levels of the classically activated marker Nos2." (PMID 31227713, 2019).
tumor (continued). "Among most upregulated genes in classical tumours, Nt5e, Tgfb1, and Arg1 have been consistently associated to T cell disfunction." (PMID 31439856, 2019). "Recruitment of ARG1-expressing MDSCs at a tumor site results in the depletion of L-arginine, which causes reduced proliferation of T-cells and NKs and inhibition of the antitumor immune response." (PMID 31695804, 2019). "Recruitment of ARG1-overexpressed MDSCs at a tumor site causes L-arginine depletion, which decreases the proliferation of T-cells and NKs and inhibition of the antitumor immune response." (PMID 31695804, 2019). "One of the key metabolites provided by the host that promotes tumor growth in the pancreas is arginine, which is degraded in autophagy-deficient mice by liver secreted arginase 1 (ARG1)." (PMID 31850344, 2019). "Increased expression of ARG1 in mouse OvCa cells is associated with accelerated tumor progression that can be blocked by an arginase inhibitor." (PMID 31278254, 2019). "MDSCs suppress the anti-tumor activity of the immune system through the activation of different genes associated with arg1 (Arginase 1), fatty acid oxidation (FAO), and ROS." (PMID 31013961, 2019). "Tumor-associated macrophages and myeloid-derived suppressor cells have been reported to inhibit T-cell activity and viability by the secretion of ARG1 and consequent depletion of arginine." (PMID 30972297, 2019). "A recent single cell transcriptomic study across human and mouse lung tumor-infiltrating immune cells showed that arginase 1 was mostly expressed by TANs and tumor-associated macrophages (TAMs)." (PMID 31616408, 2019). "Since the biological functions of ARG1 and ARG2 are identical, silencing of ARG2 (tumor suppressor) was replenished by the excessive amount of PEGylated ARG1 (BCT-100) that caused arginine depletion and suppression of tumor growth." (PMID 30808864, 2019). "Immunoblot analysis shows that co-culture with GBM ECs induced robust arginase-1 expression in human monocytes, validating the stimulatory effects of tumor-associated ECs on alternative polarization of macrophages." (PMID 29422647, 2018). "Expression of ARG-1 by myeloid cells has been unambiguously linked to tumor promoting activities, and L-ornithine was shown to further stimulate alternative activation of myeloid cells." (PMID 30233579, 2018). "In tumor-associated macrophages, a high expression of Arg1 was observed, indicating that the macrophages found in tumors are M2 macrophages." (PMID 29402936, 2018). "As expected, STAT3 signaling suppression in the tumor compartment in these autologously reconstituted humanized mice showed increased tumor infiltrating lymphocytes and reduction of arginase-1 in the stroma, which were associated with slower tumor growth rate." (PMID 28008146, 2017). "While tumor associated CD11b+/CD45high (MPs) were a small component of total Arg1+ cells (only 10–20%), almost 90% of these cells expressed Arg1." (PMID 27936099, 2016). "This suggests that the growth delay of the tumor caused by the inhibition of arg-1 is at least partially dependent on the immune system." (PMID 25869209, 2015). "Mice genetically deficient in arginase-1 or conditionally-induced to be deficient in arginase-1, succumb to an illness that mimics human arginase deficiency far too rapidly to perform tumor induction experiments examining concomitant tumor immunity." (PMID 24614600, 2014). "Arginase-1 expression by TAMs has been associated with the suppressive tumor microenvironment and shown to inhibit anti-tumor T cell responses." (PMID 24614600, 2014). "In this aspect, MDSCs in human are translated CD163+, ARG1+, and alternatively activated, tumor-associated macrophages (TAM)." (PMID 23606867, 2013). "The tumor-promoting function of MDSC is associated with increased activities of Arg-1, MMP9, and S100A8." (PMID 24453427, 2013).
tumor (continued). "Among other factors, the enzymes IDO and arginase-1 as well as TGFβ have clearly been linked to the generation and enrichment of DCreg in the tumor microenvironment." (PMID 22969767, 2012). "Arg-1 can be released or expressed by either cancer cells or tumor-associated myeloid cells, including putative MDSCs." (PMID 22481970, 2012). "PGE2 induces arginase 1 activity and arginine uptake in myeloid derived suppressor cells (MDSCs), thus causing arginine depletion in the tumor surrounding." (PMID 20856806, 2010). "Notably, the expression of Arg-1—a hallmark of M2-TAMs linked to immunosuppression and tumor progression —showed a downward trend in Arg-1+TAMs post-treatment, although statistical significance was not reached (p > 0.05)." (PMID 40670983, 2025). "Additionally, macrophages can take up lactate, which promotes their polarization into tumor-associated macrophages, leading to high expression of ARG1, which subsequently suppresses T-cell function." (PMID 40519301, 2025). "This study aimed to evaluate the association between NOS2/ARG1 expression and systemic immune cell ratios with local tumor immune infiltrates (TILs, TAMs) and to assess their prognostic significance for response to cetuximab-based chemotherapy and patient survival." (PMID 41573553, 2025). "In addition to high expression in MDSCs, ARG-1 is also upregulated in tumour-associated macrophages (TAMs) and activated neutrophils within the TME." (PMID 39861764, 2025). "Mechanistically, ALKBH5 decreased the m6A modification of Arg-1 mRNA, thereby reducing its stability and protein expression, suggesting that ALKBH5 loss in CRC may enhance Arg-1–mediated immunosuppression and tumor progression." (PMID 41562066, 2025). "Moreover, lactate drives the HIF‐1‐dependent transcription of genes encoding VEGF and the arginine‐metabolizing enzyme arginase 1, polarizing tumor‐associated macrophages toward an M2 phenotype and facilitating the immune evasion of tumor cells." (PMID 40599233, 2025). "Moreover, ARG1 activity is linked to the formation of NETs, which further promote immune evasion and tumor progression." (PMID 41208994, 2025). "Besides, secreted ARG1 from tumor-associated macrophages (TAMs) and myeloid-derived suppressor cells (MDSCs) depletes the L-arginine in TME." (PMID 40659985, 2025). "Notably, it has been reported that 25HC activates the STAT6‐dependent signaling pathway via adenosine monophosphate (AMP)‐activated protein kinase α (AMPKα), thereby promoting the expression of ARG1 in tumor‐associated macrophages (TAMs)." (PMID 41020041, 2025). "Notably, TANs promote the transcriptional expression of ARG1, leading to arginine depletion and subsequent suppression of T cell function, a critical mechanism underlying tumor immune evasion." (PMID 40342932, 2025). "In many established cancers, including OSCC, tumor-associated neutrophils (TANs) frequently assume pro-tumor functions that support angiogenesis, invasion, metastasis, and immune suppression—via arginase-1, reactive oxygen species, neutrophil extracellular traps (NETs), and checkpoint-like ligands." (PMID 41322418, 2025). "This reduction is consistent with the fact that elevated ARG1 activity leads to the loss of T-cell receptor ζ-chain expression and induces cell-cycle arrest, resulting in T-cell exhaustion hallmarks of immune-cold tumors characterized by low tumor infiltrate." (PMID 41573553, 2025). "We identified a pivotal role for the Notch signaling pathway in shaping TAM function, suggesting that T-cell dysfunction in the TME is caused when the Notch target, HES1, in TAMs is upregulated by tumor-associated factors (TAFs), which, in turn, increases the expression of arginase-1." (PMID 39702544, 2024). "Tumor cells can also upregulate and directly secrete the immunosuppressive factor indoleamine 2,3-dioxygenase-1 (IDO1) which increases expression of arginase-1 by tumor cells, causing degradation of L-arginine needed for NK and T cell survival and proliferation." (PMID 38398094, 2024).
tumor (continued). "Moreover, intratumoral injection of recombinant lytC_22 into CRC tumours promotes anti-PD1 therapy resistance in vivo by inducing intratumoral ARG1+ and iNOS+ MDSCs, thereby causing exacerbated T cell suppression." (PMID 38750176, 2024). "These divergent results suggest a context-dependent regulation of Arg-1, i.e., tumor-associated Arg-1 and soluble Arg-1 in plasma may be differently and independently regulated." (PMID 38001706, 2023). "Furthermore, ARG-1 activity is associated with polarized, protumoral M2 tumor-associated macrophages." (PMID 37376417, 2023). "LncRNAs can affect tumor associated macrophages (TAM) by regulating Arg1 expression." (PMID 37127605, 2023). "Furthermore, these cells expressed higher Arginase 1 (ARG1) levels, a marker often observed on tumor-associated, immature myeloid cells." (PMID 38022639, 2023). "Furthermore, in a follow up flow cytometry experiment we found that the frequency of F4/80+ cells expressing Arg1+, a marker associated with tumor-associated M2-like macrophage population, was also decreased by Vactosertib treatment." (PMID 37066414, 2023). "Tumor-associated neutrophils exhibit immunosuppressive function by producing ARG1 and IDO." (PMID 36831441, 2023). "Importantly, we showed that approximately 40% of tumor-associated neutrophils (TANs) actively transcribed ARG1 mRNA." (PMID 36377658, 2022). "At later time points, KCI pancreatic lesions recruited significantly fewer macrophages, a cell type associated with poor PDAC patient survival, with a specific reduction in the levels of ARG1+ macrophages, an immunosuppressive subset of tumor-associated macrophages." (PMID 35159064, 2022). "Tumor gene expression analysis performed 7 days post Imprime dosing showed upregulation of M1 markers, e.g., Nos2, Il12b, and Tnfa, along with downregulation of M2-associated genes including Arg1 and Ccl17." (PMID 35692755, 2022). "Arginase 1 (Arg1), an enzyme involved in metabolism of L-arginine and a marker for tumor-associated G-MDSC, and alternative “M2” macrophages, was produced at high levels by splenic Ly6G+ cells but not by Ly6Chi cells, further consistent with a role of Ly6Chi monocytes in pathology." (PMID 36159850, 2022). "Moreover, tumor-associated neutrophils (TANs) secrete arginase 1 (Arg-1) to degrade extracellular L-Arg, involved in the functional suppression of CD8+ T cells." (PMID 35733919, 2022). "G-MDSC could be differentiated into tumor-associated neutrophils, which immunosuppressive functions are mediated by metabolites (e.g. Arg-1, ROS, NO) and soluble regulatory factors IL-10, MMP-9, and VEGF7–9." (PMID 35589776, 2022). "Studies have also demonstrated that high PPARγ activity is also associated with a consequent increase in arginase 1 expression, suggesting KD-associated fatty acids may have similar effects on the immunosuppressive function of tumor resident macrophages." (PMID 36428642, 2022). "Tumor associated macrophages were enriched in M2 genes, Arg1, Il1rn, and Tgfb1." (PMID 35600339, 2022). "Arg1 is a key factor linked to the pathogenesis of tumor growth." (PMID 35778404, 2022). "Reducing ARG1 expression and activity may be a rational approach to counteract immunotolerant-tumour-associated macrophage effects." (PMID 36010574, 2022). "The adoptive transfer of cytokine-induced NK cells resulted in an increased myeloid-derived suppressor cell (MDSC) recruitment within tumors that impaired anti-tumor immunity through the expression of Arginase 1 and inducible nitric oxide synthase (iNOS), causing NK cell dysfunction." (PMID 34445750, 2021). "Mechanistic studies reveal that tumor-associated MDSCs in mice bearing lung carcinoma express high levels of arginase-1 and cationic amino acid transporter 2B that deplete extracellular L-Arginine, leading to downregulated expression of CD3zeta and reduced proliferation of antigen-specific T cells." (PMID 34359674, 2021).